PRAL (p53 regulation associated lncRNA)
Synonyms: lncRNA-PRAL
Gene: Gene on chromosome 17 (6,772,831 to 6,776,116, reverse strand). Ensembl gene ENSG00000279296.
Diseases named in the same sentence as PRAL in open-access papers:
PRAL is named in the same sentence as 12 diseases in open-access papers, as found by Europe PMC text mining. Sharing a sentence is not in itself a finding about the gene and the disease. The quoted sentences say what the papers report.
lung carcinoma (3 papers, 2020 to 2022).
multiple myeloma (3 papers, 2018 to 2025). "This same study further showed that PRAL potentiates the anti-multiple myeloma effects of bortezomib by sponging miR-210 and inhibiting its ability to repress expression of bone morphogenetic protein 2 (BMP2)." (PMID 39966556, 2025). "PRAL inhibits cell proliferation and induces apoptosis by targeting miR‐210 and further improves myeloma cells’ sensitivity to bortezomib." (PMID 36057947, 2023). "Another example is lncRNA PRAL, which was downregulated in primary multiple myeloma (MM) cells, especially in MM cells with del(17p)." (PMID 30466456, 2018).
diabetes (1 paper, 2022). "However, after adjusting for potential confounders, including age and sex, BMI, diabetes, hypertension, eGFR, plasma bicarbonate and PRAL, differences in urinary excretions of citrate and magnesium remained statistically significant between the study groups." (PMID 34152561, 2022).
hepatocellular carcinoma (1 paper, 2020). A malignant tumor that arises from hepatocytes. "PRAL is a hepatocellular carcinoma related lncRNA whose genomic alterations are significantly associated with hepatocellular carcinoma patient survival." (PMID 32266130, 2020).
Insulin resistance (1 paper, 2021). Increased resistance towards insulin, that is, diminished effectiveness of insulin in reducing blood glucose levels. "In the unadjusted associations between predictors and NAE, higher NAE was associated with greater GFR (3.65; 95% CI: 2.58 to 4.71; p < 0.001), increasing insulin resistance (2.50; 95% CI: 1.39 to 3.61; p < 0.001), and higher PRAL (3.22; 95% CI: 1.96 to 4.48; p < 0.001), among others." (PMID 35011042, 2021). "Finally, in the fully adjusted model, higher NAE remained directly associated with greater GFR (3.07; 95% CI: 1.87 to 4.27; p < 0.001), higher insulin resistance (1.76; 95% CI: 0.55 to 2.98; p = 0.005), and higher PRAL (1.79; 95% CI: 0.56 to 3.03; p = 0.004)." (PMID 35011042, 2021). "After multivariable adjustment, insulin resistance (1.51; 95% CI: 0.43 to 2.58; p = 0.006), GFR (2.99; 95% CI: 1.95 to 4.02; p < 0.001), and PRAL (1.78; 95% CI: 0.62 to 2.94; p = 0.003), among others, remained associated with higher NAE." (PMID 35011042, 2021).
Obesity (1 paper, 2022). Accumulation of substantial excess body fat. "The correlation of the ratio and level of interleukins from the 17 family has not been studied so far, but the literature shows that products with a high PRAL have a pro-inflammatory effect and their consumption is associated with obesity and / or type 2 diabetes." (PMID 35277002, 2022).
tumor (9 papers, 2019 to 2024). "For instance, the three stem-loop structure in lncRNA PRAL is required for its function as the molecular scaffold and tumor suppressor against HCC." (PMID 32295598, 2020). "Furthermore, it has been shown that the administration of PRAL by an adenovirus vector may noticeably lessen the growth of HCC in tumor-bearing mice, indicating that it may have potential clinical applications for the treatment of HCC." (PMID 38799446, 2024). "Hence, absence of PRAL expression or deletion of 17p13.1 locus, which encodes PRAL, was often found in human cancers correlated with PRAL tumor suppressor function." (PMID 31141943, 2019).
PRAL also shares sentences with these, for which no sentence is quoted: cancer (2 papers); heart disease (1); Hypertension (1); non-small cell lung carcinoma (1); type 2 diabetes (1).